ENSG00000251778
Gene: Small nucleolar RNA gene on chromosome 21 (41,882,205 to 41,882,300, forward strand). Ensembl gene ENSG00000251778.
Homologues: Paralogues in human: SNORA3A (79% identical), SNORA3B (56% identical), SNORA3C (55% identical).